CTLA4 (cytotoxic T-lymphocyte associated protein 4)
Diseases named in the same sentence as CTLA4 in open-access papers (continued):
Sharing a sentence is not in itself a finding about the gene and the disease.
cancer (continued). "It is known that immune checkpoints, including programed cell death protein 1 (PD-1), programed cell death ligand 1 (PD-L1) and cytotoxic T-lymphocyte-associated protein 4 (CTLA-4), can suppress the T-cell-mediated immune responses, which permits cancer cells to escape from the immune destruction." (PMID 38322419, 2024). "ICI therapy has proven to be a useful treatment for carcinoma, and we observed that the risk score was negatively correlated with the immune checkpoints CTLA4, ICOS, and PDCD1, suggesting that the sensitivity to immunotherapy may differ among subgroups." (PMID 38244579, 2024). "point out that the expression of these two immune checkpoint proteins varies across different cancers and that many cancer types demonstrate PD-1 and CTLA-4 mutations, leading to their abnormal expression, which may be used as a prognostic biomarker." (PMID 36874131, 2023). "Interestingly, low-risk groups had higher PDCD1 and CTLA4 mRNA expression than high-risk groups, which was currently commonly used for immune checkpoints in cancers." (PMID 36930113, 2023). "Combining cancer vaccines with immune checkpoint inhibitors (ICIs) such as those targeting cytotoxic T lymphocyte-associated protein 4 (CTLA-4) and programmed cell death protein 1/programmed cell death ligand 1 (PD-1/PD-L1) is one approach to avoid T cell anergy." (PMID 37397557, 2023). "Immune checkpoint inhibitors (ICIs), including cytotoxic T-lymphocyte antigen 4 (CTLA-4), programmed cell death 1 (PD-1), and its ligand 1 (PD-L1), have improved the survival in multiple types of cancers; however, ICIs may cause cardiovascular toxicity." (PMID 37305530, 2023). "One treatment approach involves the boosting of the host’s suppressive ability against cancer cells as demonstrated by immune checkpoint inhibitors including anti-cytotoxic T-lymphocyte associated antigen-4 (CTLA-4) and programmed death -1 (PD-1; pembrolizumab) and PD ligand-1 (PD-L1; atezolizumab)." (PMID 37041200, 2023). "Thus, specific blockade of the immune checkpoints cytotoxic T-lymphocyte-associated protein 4 (CTLA-4) or programmed cell death protein 1 (PD-1) has shown potential in the treatment of different types of cancer by promoting T cell responses in patients." (PMID 37965326, 2023). "Cancer cells may escape the host immune response by expressing immune checkpoint molecules, such as cytotoxic T-lymphocyte associated antigen 4 (CTLA-4) and programmed death ligand 1 (PD-L1), which block T-cell activation and proliferation." (PMID 37256537, 2023). "This CTLA-4 polymorphism study may therefore provide useful insights and suggestions for specific immunotherapy applications for cancer." (PMID 38046481, 2023). "Notably, the inhibition of cytotoxic T lymphocyte-associated antigen 4 (CTLA-4) became the first successful checkpoint blockade in cancer immunotherapy, highlighting the critical role of costimulatory signaling in T-cell activation." (PMID 37667784, 2023). "On the other hand, PD-1, PD-L1, and cytotoxic T-lymphocyte-associated protein 4 (CTLA-4) might modulate the metabolic functions of cancer and infiltrating immune cells." (PMID 37525297, 2023). "One major breakthrough in cancer immunotherapy has been the identification of immune checkpoint molecules in tumors, namely cytotoxic T-lymphocyte-associated protein 4 (CTLA-4), the programmed cell death-1 (PD-1), and its ligands programmed death-ligand 1 (PD-L1) and PD-L2." (PMID 37367867, 2023). "In recent years, immune checkpoint inhibitors that target PD-1/PD-L1 and/or cytotoxic T lymphocyte-associated antigen-4 (CTLA-4) have emerged as effective immunotherapeutic agents in several types of cancer, profoundly changing the prognosis of a fraction of patients." (PMID 37234161, 2023).
cancer (continued). "ICIs target programmed cell death-1 (PD-1), PD ligand-1 (PD-L1), and cytotoxic T-lymphocyte-associated antigen-4 (CTLA-4), with a subsequent disruption of the host T cell signaling and the upregulation of the T cell immune innate and adaptive response against cancer cells." (PMID 37175898, 2023). "Immune checkpoint inhibitors, that is, antibodies blocking cytotoxic T-lymphocyte associated protein 4 (CTLA-4), programmed cell death 1 (PD-1) as well as its ligand PD-L1, have been approved by regulatory agencies around the world to treat multiple human cancer types." (PMID 37881432, 2023). "ICIs interrupt co-inhibitory signaling pathways mediated by programmed cell death protein 1 (PD-1), programmed cell death protein ligand 1 (PD-L1) and cytotoxic T lymphocyte-associated antigen (CTLA-4) that result in the elimination of cancer cells by stimulating the immune system." (PMID 36769297, 2023). "Therapeutic blockade of the programmed cell death protein 1 (PD-1) and the cytotoxic T-lymphocyte associated protein 4 (CTLA-4) immune checkpoints has emerged as a powerful strategy for cancer treatment in multiple cancer types by reinvigorating exhausted T cells 1,2." (PMID 36778120, 2023). "Cancer immunotherapy has revolutionized cancer treatment both as monotherapy or in combination strategies, especially ICIs that block cytotoxic T lymphocyte‐associated protein‐4 (CTLA‐4) and the PD‐1/PD‐L1 axis." (PMID 37732493, 2023). "Specifically, the regulation of the immune system through immune checkpoint blockade (ICB), most notably via cytotoxic T-lymphocyte-associated protein 4 (CTLA-4) and programmed death-1 (PD-1), is the most clinically advanced type of immunotherapy and is approved for multiple cancers." (PMID 36672243, 2023). "Additionally, the expression level of CTLA4 has been associated with prognosis and response to immunotherapy in different cancer types." (PMID 37798374, 2023). "Considering the genetic variants of CTLA-4 rs11571317 (−658 C>T) and its role in the maintenance of immunological balance, it has the potential to modify the immune responses and susceptibility to the development of cancer." (PMID 38186404, 2023). "PTPN7 has been associated with CTLA-4 and PD-L1 expression in almost all cancer types." (PMID 37685980, 2023). "Recent studies have demonstrated that certain patterns of DNA methylation could be used as a predictive biomarker in response to PD-1 (programmed-death-1) inhibitors and CTLA-4 (cytotoxic T-lymphocyte-associated protein 4) inhibitors in different cancer types." (PMID 37835379, 2023). "Additionally, our results showed a significant correlation between PCSK9 expression with PDCD1 and CTLA4, which referred to T cell exhaustion and led to the loss of T cell function in patients with common chronic infections and cancer." (PMID 37860186, 2023). "ICIs have been a hot topic in cancer treatment research in recent years, primarily targeting programmed cell death-1 (PD-1) or programmed cell death ligand-1 (PD-L1) and cytotoxic T-lymphocyte-associated antigen-4 (CTLA-4) in the body’s immune process." (PMID 37799725, 2023). "The introduction of treatments with immune checkpoint inhibitors (ICIs), which target the CTLA-4 (Cytotoxic T-Lymphocyte Associated Protein 4) and PD-1/PD-L1 (Programmed Cell Death-1/Programmed Death-Ligand 1) pathways, among others, has been a breakthrough in the fight against cancer." (PMID 37998729, 2023). "We retrieved the clinical data of LUAD patients treated with CTLA-4 or/and PD-1 from The Cancer Immunome Atlas (TCIA) database and observed that high-risk patients may benefit more from immunotherapy." (PMID 37955668, 2023). "The Canadian Cancer Trials Group CO.26 study assessed the effect of combined immune checkpoint inhibition with anti-cytotoxic T-lymphocyte-associated protein (CTLA)-4 and anti-PD-L1 blockade compared with that of the best supportive care alone in patients with advanced CRC." (PMID 36982838, 2023).
cancer (continued). "In addition to anti-PD-1/PD-L1 or anti-CTLA-4 treatment strategies, tumour-associated macrophages (TAMs) and cancer-associated fibroblasts (CAFs) have also been previously reported as potential strategies for cancer treatment research." (PMID 36925653, 2023). "Over the last few decades, immune checkpoint inhibitors (ICIs) against programmed death receptor 1 (PD-1), programmed death receptor ligand 1 (PD-L1), and cytotoxic T lymphocyte-associated antigen-4 (CTLA-4) have emerged as a revolutionary option for cancer treatment." (PMID 37207161, 2023). "The field of cancer immunotherapy has grown rapidly with the clinical application of checkpoint inhibitors (CPIs), particularly programmed death-1/programmed death ligand-1 (PD-1/PD-L1) and cytotoxic T-lymphocyte-associated protein-4 (CTLA-4)." (PMID 37046612, 2023). "Indeed, it has been shown that a cocktail of IDO1 inhibitors and immunotherapeutic drugs, including agents targeting cytotoxic T lymphocyte-associated protein 4 (CTLA4) or PD-1, displays a synergistic effect in combating cancer." (PMID 37895133, 2023). "CRISPR/Cas9-mediated genome editing can be used to remove genes that encode inhibitory T-cell surface receptors, such as cytotoxic T-lymphocyte-associated protein 4 (CTLA-4) and programmed cell death protein 1 (PD-1), to increase the effectiveness of T-cell-based immunotherapy in treating cancer." (PMID 36826113, 2023). "High expression of CTLA-4 was observed to be associated with a worse prognosis in many cancers, including PCa, and the intervention of CTLA-4 blockers could improve prognosis of patients." (PMID 37270661, 2023). "By disabling immune checkpoints, such as those regulated by cytotoxic T-lymphocyte-associated protein 4 (CTLA-4) or programmed cell death-1 (PD-1), cancer immunotherapies stimulate the activity of immune cells that can thereby promote the clearance of cancer cells." (PMID 36743451, 2023). "ICIs are indicated for use in diverse cancer types and include monoclonal antibodies that target the immune checkpoint proteins programmed death receptor-1 (PD-1), programmed death ligand-1 (PD-L1), and cytotoxic T-lymphocyte-associated protein 4 (CTLA-4)." (PMID 37174018, 2023). "The most widely used immunotherapies that have proven clinical efficacy across a wide range of cancers are immune checkpoint inhibitors (ICIs) targeting programmed cell death 1 (PD-1), PD-L1, cytotoxic T lymphocyte-associated antigen 4 (CTLA-4) and lymphocyte activation gene-3 (LAG-3)." (PMID 36945046, 2023). "One of the major breakthroughs in cancer immunotherapy was the identification of immune checkpoint molecules, cytotoxic T-lymphocyte-associated protein 4 (CTLA-4), the programmed cell death-1 (PD-1), and its ligands programmed death-ligand 1 (PD-L1) and PD-L2 tumors." (PMID 37237922, 2023). "Furthermore, the results showed that NKTR-214 enhanced persistence and antitumor immunity in combination with an anti-cytotoxic T lymphocyte-associated antigen-4 (CTLA-4) antibody in preclinical cancer models." (PMID 37177365, 2023). "Application of monoclonal antibodies targeting immune checkpoints, such as programmed cell death 1 ligand 1 (PD-L1), integrin-associated protein (CD47) and cytotoxic T lymphocyte associated antigen 4 (CTLA-4) has been found to improve the survival rate of patients with several cancer types." (PMID 35413927, 2022). "Monoclonal antibodies inhibiting the T cell checkpoints CTLA-4 (Cytotoxic T-Lymphocyte Associated Protein 4) and PD-1 have shown antitumor immune responses, resulting in pronounced efficacy in a small percentage of patients with cancer." (PMID 35179953, 2022). "Immune-checkpoint inhibitors (ICIs), such as the blocking antibodies of programmed cell death protein-1 (PD-1), programmed death-ligand 1 (PD-L1), and cytotoxic T lymphocyte-associated protein 4 (CTLA-4), have brought considerable clinical benefits to cancer patients." (PMID 36341331, 2022).
cancer (continued). "Indeed, combined anti-CTLA-4 and anti-PD-1 blockade can overcome the larger immune incline presented by less immunogenic cancers and associated poorer T cell activation resulting from exposure to low affinity antigens." (PMID 36175961, 2022). "In the landscape of cancer immunotherapies, therapeutically targeting immune inhibitory checkpoints through the blockade of cytotoxic T-lymphocyte-associated protein 4 (CTLA-4), programmed cell death protein-1 (PD-1), and programmed death ligand-1 (PD-L1) are most broadly effective." (PMID 35720282, 2022). "The advent of immune-checkpoint inhibitors (ICIs) which block cytotoxic T lymphocyte-associated protein-4 (CTLA-4) and the programmed death-1 (PD-1)/programmed death ligand-1 (PD-L1) axis, both as monotherapy or in combination strategies, have revolutionized cancer treatment." (PMID 35865949, 2022). "There have been promising advances in cancer immunotherapy with the blockade of ICRs, such as programmed cell death 1 (PD-1), programmed death-ligand 1 (PD-L1), and cytotoxic T-lymphocyte-associated protein 4 (CTLA-4)." (PMID 36271406, 2022). "The development of immunotherapeutics and immune checkpoint inhibitors, such as anti-cytotoxic T-lymphocyte-associated protein 4 (CTLA-4) and anti-programed death 1 (PD-1) molecules are being studied in clinical trials for the treatment of different types of cancer." (PMID 35408830, 2022). "In our previous studies, we found that the rs231775 polymorphism of cytotoxic T-lymphocyte antigen 4 (CTLA-4) is associated with risks of different cancer types; however, the association remains controversial and ambiguous, so we conducted an in-depth meta-analysis to verify the association." (PMID 35600409, 2022). "In recent years, the field of cancer immunotherapy has seen considerable progress due to the discovery of new therapies targeting immune checkpoint molecules such as cytotoxic T lymphocyte-associated protein 4 (CTLA-4), programmed cell death 1 (PD1) and programmed cell death ligand 1 (PD-L1)." (PMID 35840912, 2022). "According to the results, CTLA-4 rs231775 is strongly associated with the maximum cancer risk." (PMID 35600409, 2022). "Other case reports of PWH on ART receiving anti-PD-1 or anti-CTLA-4 for cancer have described transient increases in either cell-associated or plasma HIV RNA with or without a decrease in the frequency of latently infected CD4+ T-cells, whereas others have not seen this effect." (PMID 35123267, 2022). "In recent decades, one of the major breakthroughs in cancer immunotherapy has been the discovery of immune checkpoint molecules, such as cytotoxic T-lymphocyte-associated protein 4 (CTLA-4), programmed cell death-1 (PD-1) and its ligand [programmed death-ligand 1 (PD-L1)]." (PMID 36284271, 2022). "Recently, cancer immunotherapy using immune‐checkpoint blockade (ICB) that targets programmed cell death 1 (PD‐1), programmed cell death‐ligand 1 (PD‐L1), programmed cell death‐ligand 2 (PD‐L2) and cytotoxic T‐lymphocyte‐associated protein 4 (CTLA‐4) provides significant clinical benefits in cancer." (PMID 34894053, 2022). "Immune checkpoint inhibitors (ICIs) such as programmed death-ligand 1/programmed death-1 (PD-L1/PD-1) blockade and cytotoxic T-lymphocyte-associated protein 4 (CTLA-4) inhibitors are another representative breakthrough in cancer immunotherapy that has been successfully used in solid tumors." (PMID 36105816, 2022). "In mouse cancer models, researchers identified that anti-CTLA-4 treatment strategies could cause tumor regression and lead to resistance to reinoculation of malignant cells." (PMID 35585975, 2022). "The identification of proteins that suppress T cell responses such as Cytotoxic T-lymphocyte-associated protein 4 (CTLA-4), programmed death-ligand 1 (PD-1) and its ligand PD-L1 opens up new opportunities for treating certain cancers having elevated production of such proteins." (PMID 36046747, 2022).
cancer (continued). "Hif-1α supports cancer cell survival under hypoxic conditions through its activation of nuclear factor kappa B (NF-κB) as well as promotion of expression of ligands for program death receptor 1 (PD-1) and cytotoxic T-lymphocyte-associated protein 4 (CTLA-4)." (PMID 35216362, 2022). "ICIs amplify T-cell-mediated immune responses against cancer cells by blocking intrinsic immune down-regulators such as anti-cytotoxic T-lymphocyte associated protein 4 (CTLA-4), programmed cell death protein-1 (PD-1), and programmed cell death ligand-1b (PD-L1)." (PMID 36698405, 2022). "ICIs are humanized monoclonal antibodies that can activate T cells and relieve the immune system to recognize and assault cancer cells by targeting cytotoxic T-lymphocyte-associated protein 4 (CTLA4) (CD152), programmed cell death protein 1 (PD-1), or programmed cell death ligand-1 (PD-L1)." (PMID 35884501, 2022). "CTLA-4 and PD-1 expression is upregulated upon T cell activation and the latter has been associated with T cell functional exhaustion in both chronic viral infections and cancer." (PMID 35874810, 2022). "Another major breakthrough in treating cancers generally has been the emergence of immune checkpoint inhibitors (ICIs) including antibodies targeting cytotoxic T-lymphocyte-associated protein 4 (CTLA-4) or programmed cell death-1/programmed cell death ligand 1 (PD-1/PD-L1)." (PMID 36359830, 2022). "These monoclonal antibodies are directed against the inhibitory immune receptors cytotoxic T-lymphocyte-associated protein-4 (CTLA-4) and programmed death-1 (PD-1) and enhance the immune function of T-cells, thus mobilizing the body’s immune cells to selectively target cancer cells." (PMID 36685586, 2022). "Indeed, CTLA-4 variants are recognised to cause immune dysregulation disorders and CTLA-4 blockade is employed in cancer therapy." (PMID 34097529, 2021). "Immunotherapy (IT) and especially immune checkpoint blockade with PD1-(programmed cell death-1)/programmed cell death-ligand 1 (PD-L1) and CTLA-4 (cytotoxic T-lymphocyte-associated Protein 4) inhibitors have invaded the clinical routine and is revolutionizing the treatment of cancer." (PMID 33828117, 2021). "Cancer immunotherapy using antibodies that interfere with co-inhibitory molecules such as cytotoxic T-lymphocyte-associated protein 4 (CTLA-4) or programmed cell death protein 1 (PD-1) and its ligand programmed death-ligand 1 (PD-L1) has revolutionized the treatment of various cancer entities." (PMID 34112740, 2021). "The identification/characterization of immune checkpoint molecules, i.e., programmed cell death protein 1 (PD1), programmed cell death ligand 1 (PDL1), and cytotoxic T lymphocyte-associated antigen 4 (CTLA4), represents a major advancement in the field of cancer immunotherapy." (PMID 34094935, 2021). "Furthermore, cancer cell-mediated upregulation of CTLA-4 (anti-cytotoxic T-lymphocyte-associated antigen 4) on T-cells enhances the recruitment of immunosuppressive T-cells and constitutes a co-inhibitory pathway to elude host immune responses." (PMID 33673374, 2021). "All in all, CTLA-4 contributes to the immune deficiency observed in cancer patients." (PMID 34236546, 2021). "There is evidence of gastrointestinal side effects in cancer patients treated with anti-CTLA-4 antibody, associated with an increased expression of the biliary glycoprotein CECAM-1 and the cell surface glycoprotein CD177, which is directly correlated with neutrophil activation." (PMID 34790123, 2021). "Overall, the advent of CTLA-4 and PD-1 immune checkpoint inhibitors dramatically shifted the field of cancer therapeutics and prompted the inclusion of immune evasion as a hallmark of cancer." (PMID 34025662, 2021).